CD4 (CD4 molecule)
Diseases named in the same sentence as CD4 in open-access papers (continued):
Sharing a sentence is not in itself a finding about the gene and the disease.
amyotrophic lateral sclerosis (12 papers, 2013 to 2026). Amyotrophic lateral sclerosis (ALS) is a neurodegenerative disease characterized by progressive muscular paralysis reflecting degeneration of motor neurons in the primary motor cortex, corticospinal tracts, brainstem and spinal cord. "Brain antigen specific Th1 CD4+ T cells (INFγ−producing cells) at the CP were reported to be beneficial to the brain during neuro-inflammation associated with various neurodegenerative conditions including Amyotrophic Lateral Sclerosis (ALS), MS, PD, and AD." (PMID 27738345, 2017). "Similar neuroprotective functions of CD4+ T cells have been described in other chronic neurodegenerative conditions, such as amyotrophic lateral sclerosis." (PMID 41596612, 2026). "In the context of late-stage Amyotrophic Lateral Sclerosis (ALS), there is growing evidence that CD4+ T cells infiltrating the blood–brain barrier exhibit signs of advanced aging." (PMID 39194682, 2024). "Crucial to the neuroinflammatory modulation, T regulatory cells (Tregs), a subset of T cells characterized by expression of CD4+, FoxP3+, CD25+, are known as potential modifiers of disease progression in Amyotrophic Lateral Sclerosis (ALS)." (PMID 39845951, 2024). "Amyotrophic lateral sclerosis patients presented with significantly altered proportions of monocyte subsets in peripheral blood and increased frequencies of CD4+ and CD8+ T cells expressing the activation marker HLA-DR in peripheral blood (CD8+) and CSF (CD4+ and CD8+) compared with controls." (PMID 34405141, 2021).
anaplastic large cell lymphoma (12 papers, 2013 to 2026). Anaplastic large cell lymphoma (ALCL) is a rare and aggressive peripheral T-cell non-Hodgkin lymphoma, belonging to the group of CD30-positive lymphoproliferative disorders, which affects lymph nodes and extranodal sites. "In childhood, ALK-positive anaplastic large cell lymphoma is a major type of CD4- and TIA1-positive cytotoxic T/NK-cell lymphoma." (PMID 23302373, 2013). "Surgical excision and biopsy revealed a dense dermal and subcutaneous infiltrate of large atypical lymphoid cells with strong and diffuse CD30 expression (~80%-90% of tumor cells), CD4 positivity, ALK-negativity, and loss of pan-T-cell markers, consistent with anaplastic large cell lymphoma (ALCL)." (PMID 42017675, 2026). "Given the rarity of phenotypical shift in this direction in CTCL, the following report is the first of its kind to specifically describe this CD8+ to CD4+ immunophenotypic shift in MF with concurrent large cell transformation to ALK-negative anaplastic large cell lymphoma." (PMID 40166794, 2025). "Notably, this case had high expression of CD30 (normalized count = 8471.48, mean = 358.98, standard deviation = 1622.66), a feature of anaplastic large cell lymphoma, which may have accounted for its clustering away from the typical canine CD4+ PTCL cases." (PMID 38166662, 2024). "For anaplastic large cell lymphoma, the use of CD3 and other T-cell markers, as well as CD4, CD8, ALK, and CD30, is helpful for diagnosis." (PMID 37958219, 2023). "For anaplastic large cell lymphoma, the use of CD3 and other T-cell markers, as well as CD4, CD8, CD20, PAX5, ALK, and CD30, are helpful for diagnosis." (PMID 37958219, 2023). "Our case report describes another instance of CD8+ to CD4+ phenotypic shift of MF, but with associated transformation to anaplastic lymphoma kinase (ALK)-negative anaplastic large cell lymphoma (ALCL) - the first documented case of its kind." (PMID 40166794, 2025). "The present case is a CD3-, CD4- and TIA1-positive and CD30-negative (Th1) large-cell lymphoma without EBV infection." (PMID 23302373, 2013).
cervical squamous cell carcinoma (12 papers, 2002 to 2025). A squamous cell carcinoma arising from the cervical epithelium. "Studies carried out on cervical squamous cell carcinoma showed that MMP1 is inversely related to CD4, CD8, and macrophage activity in the tumor microenvironment." (PMID 35083113, 2022). "Moreover, activated memory CD4 + T cells are considered an element of the favorable outcomes about patients with cervical squamous cell carcinoma, whereas resting memory CD4 + T cells are considered an element of the adverse outcomes." (PMID 36185274, 2022). "In cervical squamous cell carcinoma (CESC), ACSS2 expression is associated with infiltration of B cells, CD4+ and CD8+ T cells, and cancer-associated fibroblasts (CAFs), and high ACSS2 expression is associated with shorter overall survival times." (PMID 35798917, 2022). "Subsequently, flow cytometry was utilized to assess the expression levels of PD-1 in CD4+ T cells and CD8+ T cells isolated from CESC (cervical squamous cell carcinoma) model mice and normal mice." (PMID 40539049, 2025). "Immunohistochemistry and immunofluorescence staining were used to detect B7-H4, Foxp3, CD4, CD8, and interferon-γ in the 75 pairs of specimens obtained via biopsy; 20 samples were found to have chronic cervicitis, and another 20 had squamous cell carcinoma of the cervix." (PMID 34651047, 2021). "In a previous study we found a striking difference in the numbers of both intra- and peritumoural CD3+, CD4+ and CD8+ cells in biopsies between women who were cured by primary treatment for stage IB cervical squamous cell carcinomas and women who experienced a relapse." (PMID 17940503, 2007). "Quantification of the total amount of cells as well as the expression of CD3, CD4, CD8, CD25 and tryptase in the stromal inflammatory compartment were analysed in nine squamous cervical cancers randomly chosen among cases with high (>1) vs low (⩽1) tumour/stroma COX-2 IDV ratio." (PMID 12402155, 2002).
dilated cardiomyopathy (12 papers, 2012 to 2025). Cardiomyopathy which is characterized by dilation and contractile dysfunction of the left and right ventricles. "Moreover, CD4 T cell-mediated autoimmune responses can induce a Th17-dependent pro-inflammatory cascade, which is linked to the development of dilated cardiomyopathy." (PMID 37512058, 2023). "Research conducted by Guo and colleagues has highlighted the significant role of CD4+ effector T cells producing IL-22, also known as Th22 cells, in the progression of chronic myocarditis and dilated cardiomyopathy in mice infected by CVB3." (PMID 37512058, 2023). "The hsa-miR-451a was also discovered as a down-regulated miRNA in patients with dilated cardiomyopathy, which facilitated the activation and proliferation of CD4 + T cells by targeting Myc." (PMID 36859746, 2023). "For instance, in dilated cardiomyopathy (DCM), miRNA-3064-5p, miRNA-6849-5p and miRNA-4701-3p are upregulated in abnormal activated CD4 + T cells, which may be associated with the proliferation of CD4 + T cells." (PMID 34044888, 2021). "All five patients with dilated cardiomyopathy (DCM) had a CD4 count < 200/μl." (PMID 22907266, 2012). "This study found CD4+, CD8+ T cells, and activated macrophages in the hearts of dilated cardiomyopathy (DCM) patients, consistent with previous findings." (PMID 40808946, 2025). "In mice with dilated cardiomyopathy, pharmacologic antagonism of stromal cell-derived factor-1/CXCR4 signaling with AMD3100 was shown to decrease splenic CD4 + T cell abundance and cardiac fibrosis and improve diastolic and systolic myocardial performance." (PMID 35048778, 2022). "Evidence has revealed that CD4+CD25+GARP+ Tregs derived from humans can reduce the proliferation of Tregs and influence the secretion of pro-inflammatory cytokines, such as IFN-γ and IL-17, in people suffering from dilated cardiomyopathy." (PMID 37512058, 2023).
Encephalopathy (12 papers, 2013 to 2025). Encephalopathy is a term that means brain disease, damage, or malfunction. "For T cells, our analysis found that most T cell subtypes were associated with encephalopathy recovery status, while two proliferative T cells subsets (CD4_Pro and CD8_Pro) displayed distinct associations with COVID-19 encephalopathy types." (PMID 37848421, 2023). "Key laboratory findings included significantly lower levels of interferon-gamma (IFN-γ) (P < .001), tumor necrosis factor-alpha (TNF-α) (P < .001), and a decreased CD4+/CD8 + ratio (P = .001) compared to the non-encephalopathy group." (PMID 41189156, 2025). "CD4+ T cells are linked to encephalopathy, myelitis and cerebellar syndrome, while CD8+ T cells and B cells are associated with myelitis and encephalopathy." (PMID 40918112, 2025). "Patients with DM and encephalopathy had an increased percentage of CD4+ PD-1+ compared to remission patients with DM (14.9% [10.2–15] vs. 1.58% [0.71–1.84] p = 0.048)." (PMID 40150045, 2025). "CD4+PD-1+ and CD8+PD-1+ T cell expansion is the distinctive hallmark of DM subjects with encephalopathy in comparison to remission and active DM patients." (PMID 40150045, 2025). "More cytotoxic (CD8 positive) than helper (CD4 positive) lymphocytes were found in the white matter of the encephalopathy group." (PMID 28072884, 2017). "We detected a significantly higher number of CD8 positive cells than CD4 positive cells in both gray (p = 0.026) and white matter (p = 0.007) of the encephalopathy group." (PMID 28072884, 2017). "Child 2 was born with encephalopathy (CDC clinical stage C1) but with normal CD4+ T cell percentage (52%) and undetectable viral load." (PMID 24156513, 2013). "In patients with DM-related encephalopathy and with DM in remission, the percentage of naïve CD4+ T cells was increased in comparison to healthy controls (HC) (56.6% [26.8–76.5] vs. 6.43% [4.52–8.8] p = 0.011), and (43.8% [35.8–43.8] vs. 6.43% [4.52–8.8] p = 0.021) respectively." (PMID 40150045, 2025). "In comparison to healthy controls, DM patients with encephalopathy had increased naïve CD4+, CD57+, and CD4+ T cells, effector memory (TEM), and CD73+ and CD8+ T cells." (PMID 40150045, 2025). "CD4+CD57+ and CD8+CD73+ T cell subsets are expanded in DM patients with encephalopathy compared to HC." (PMID 40150045, 2025). "Th17 cells, another subset of CD4+ Th cells, have now been characterized as a unique CD4+ T lineage with distinct secretion of IL-17, IL-21, IL-9, IL-22, and TNF-α, of which IL-17 is the most important cytokine in Th17-mediated encephalopathy." (PMID 39329740, 2024). "This group displayed markedly lower levels of IFN-γ (P < .001), TNF-α (P < .001), and a decreased CD4+/CD8+ ratio (P = .001) compared to the no encephalopathy group." (PMID 41189156, 2025). "The peripheral immunophenotype of DM patients with encephalopathy demonstrated enhanced expression of PD-1+ in CD4+ and CD8+ T cells in comparison with DM patients without encephalopathy." (PMID 40150045, 2025).
giant cell arteritis (12 papers, 2018 to 2026). "In giant cell arteritis, a large vessel vasculitis, there is accumulating evidence for a pathogenic role of IL-17 and Th17 cells, which are part of the CD4+ T-cell subset." (PMID 38299156, 2023). "Giant cell arteritis is a CD4+T-cell-mediated autoimmune systemic vasculitis of the medium and large arteries, with a predilection for the posterior ciliary arteries." (PMID 41464193, 2025). "Here, the authors also showed via transcriptomic data that CTLA-4-related pathways are upregulated in the circulating CD4+ T-cell compartment of patients with giant cell arteritis, while in aortic samples, gene expression of CD4+ T cells was also altered." (PMID 39023770, 2025). "Giant cell arteritis (GCA) is a large vessel vasculitis with a pathogenesis that involves two CD4 T-helper cell lineages, Th1 and Th17." (PMID 33754114, 2021). "Through single-cell analysis, we focused on the CD4+ Memory T cells in giant cell arteritis." (PMID 39762453, 2025). "In patients with giant cell arteritis (GCA), frequencies of circulating CD8+ Treg cells are largely maintained, but an altered gene expression program results in impaired suppressive capacity and unopposed inflammatory activity of pathogenic CD4+ T cells." (PMID 35296082, 2022). "The IFI44L gene has substantial upregulation in CD4+ and CD8+ T cells of patients with large-vessel involvement in giant cell arteritis (LV-GCA)." (PMID 39737399, 2024). "Specifically, CD4+ T cells are triggered by class-II major histocompatibility complex (MHC-II) and co-stimulatory molecules (CD80 and CD86), then infiltrated all the layers of the artery, leading to pan-arteritis." (PMID 39762453, 2025). "CD4+ and CD8+ T cells in giant cell arteritis and in Takayasu arteritis." (PMID 33072134, 2020). "The role of CD4+ Memory T cells in giant cell arteritis has not been elucidated." (PMID 39762453, 2025).
Hyponatremia (12 papers, 2013 to 2026). An abnormally decreased sodium concentration in the blood. "Univariate analysis of baseline characteristics showed lower admission GCS, infarcts, extra-meningeal TB, VPS infection, lower CD4 count, and hyponatremia as factors trending towards association with mortality." (PMID 37964056, 2024). "Our study further showed that after adjustment for age, WHO stage, CD4 count, hemoglobin and albumin in a multivariate model, severe/moderate hyponatremia remained a high risk factor for death." (PMID 25360785, 2014). "Laboratory evaluation revealed a viral load of 327,000 copies/mL and severe immunosuppression with a Cluster of Differentiation (CD4) count of 8 cells/μL, hyponatremia, and elevated liver transaminases." (PMID 41664717, 2026). "The case presented a 58‐year‐old Hispanic woman with HIV, managed on bictegravir/emtricitabine/tenofovir alafenamide with an undetectable viral load and a CD4 count of 31, who experienced cyclical fevers accompanied by transaminitis, hyperbilirubinemia, and hyponatremia." (PMID 41425512, 2025). "After adjusting for sex, age, WHO stage, CD4 count, hemoglobin and albumin, the relative hazard was 3.5 (95% CI: 1.9–6.5) for patients with moderate/severe hyponatremia (P<0.001), and 1.5 (95% CI: 0.9–2.4) for those with mild hyponatremia (P = 0.161), compared with normonatremic patients." (PMID 25360785, 2014). "Interestingly, in contrast to the previously cited studies, hyponatremia was not an independent risk factor for mortality in our analysis, even after restricting the analysis to patients with advanced HIV disease (CD4 < 200/μl)." (PMID 28122494, 2017).
IgA nephropathy (12 papers, 2014 to 2026). "Previous immunological study has demonstrated that elevated numbers of lymphocytes, increased percentages of activated CD8+ T lymphocytes and CD4+ T lymphocytes in IgA nephropathy patients were observed, compared to healthy individuals." (PMID 38828235, 2024). "We comparatively studied the immunohistochemical expression of FOXP3+ Tregs, CD4+ and CD3+ T cells in IgA nephropathy (IgAN), focal segmental glomerulosclerosis (FSGS), and membranous glomerulopathy (MGN)." (PMID 34336285, 2021). "Furthermore, CD122 expression on CD4+ T cells and CD25+ CD4+ T cells and CD25neg CD4+ T cells was not different between HC and patients with IgA-nephropathy (CD4+ T cells: %CD122+47 ± 13% versus 44 ± 11%, ns; CD4+CD25+: 62 ± 9% versus 56 ± 9%, ns; CD4+CD25neg: 44 ± 14% versus 41 ± 10%, ns)." (PMID 24648606, 2014).
Interstitial pneumonitis (12 papers, 2005 to 2023). "In a mouse SARS‐CoV model, it seems that the depletion of CD4+ T cells at the time of infection leads to enhanced immune‐mediated interstitial pneumonitis and delayed viral clearance." (PMID 37773701, 2023). "Depletion of CD4+ T cells has been shown to delay the virus clearance and enhance immune-mediated interstitial pneumonitis and reduce a neutralizing titer in the lungs of SARS-CoV-infected mice." (PMID 34108961, 2021). "T-cell abnormalities in patients with ExRA include expansion of CD8+ large granular lymphocytes and of immunosenescent CD4+CD28- cells, and extensive CD4+ infiltrates in RA-associated interstitial pneumonitis." (PMID 16277691, 2005). "A previous study found that in a SARS-CoV infected mouse model, depletion of CD4 but not CD8 T cells lead to enhanced immune-mediated interstitial pneumonitis and delayed clearance of SARS-CoV from the lung." (PMID 34251989, 2021). "Indeed, according to mouse model experiments, in the absence of CD4+ there was much more severe interstitial pneumonitis, whereas the depletion of both CD4+ and CD8+ led to an increase of neutrophils and macrophages in the lesions." (PMID 33329516, 2020).
intestinal tumors (12 papers, 2005 to 2026). "In contrast to these data, the intestinal tumors which are strongly associated with an inflammatory microenvironment regress after injection of CD4+CD25+ T regulator cells." (PMID 16188028, 2005). "In addition, the number of immuno-suppressive, pro-tumorigenic CD4+Foxp3+ Treg cells increased in myeloid Mir34a-deficient intestinal tumors." (PMID 42140945, 2026). "Organoids were generated from intestinal tumors of APCmin mice, a spontaneous model of multiple intestinal tumors, and co-cultured with CD4+ T cells and CD3+ T cells from SP and IEL of young and old mice to investigate the cytotoxic potential." (PMID 38327516, 2024). "To investigate the role of old IEL CD4+ T cells in intestinal tumor immunity, we examined their anti-tumor cellular immunity in vitro." (PMID 38327516, 2024). "Yet, additional studies are warranted to definitively address the function of IL-33/ST2 signaling for CD4+ T cell plasticity in the intestinal tumor environment." (PMID 31165767, 2019). "Taken together, these observations complement our previous observation of increased CXCR3 ligand expression in tumors after Treg depletion, and underline the specific importance of CXCR3 in lymphocyte, and more specifically CD4+ T cell, migration into intestinal tumors." (PMID 29671006, 2018). "Both P-selectin expression on tumor endothelial cells and PSGL-1+ expression on tumor-infiltrating CD4+ T cells were significantly higher compared to small intestine suggesting that this pathway may contribute to T-cell recruitment into intestinal tumors." (PMID 29671006, 2018). "Furthermore, adoptive immunotherapy with CD4+CD25+ Tregs has been shown to decrease tumor multiplicity through induction of apoptosis in intestinal tumors, which supports the possibility that in certain contexts, Tregs can directly or indirectly eradicate tumor cells." (PMID 22879926, 2012). "Similarly, compared with the model group, the proportions of lymphocytes, B cells, T cells, natural killer T cells, CD3+CD4+ T cells, and CD3+CD8+ T cells in the intestinal tumors of the JK5G mice were significantly increased (p < 0.05)." (PMID 33178591, 2020). "AOM/DSS-treated chimeras with ST2-deficient hematopoietic cells had no alteration in CD4+ T cell frequencies, yet they showed a reduction of CD4+ FOXP3+ Tregs in intestinal tumors." (PMID 31165767, 2019). "This is the first time CXCR3 has been shown to be non-redundant for CD4+ T-cell migration into intestinal tumors, even though earlier results have indicated that CXCL9 and CXCL10 significantly correlate to disease free survival of CRC patients, and also to the recruitment of memory T cells." (PMID 29671006, 2018). "When densities of γδ T cells infiltrating the intestinal tumor and surrounding stroma were determined, we found somewhat more gd T cells in the stroma than in the tumor masses, but the difference was not as pronounced as with conventional CD4+ and CD8+ T cells." (PMID 36900249, 2023).